ABCB1 (ATP binding cassette subfamily B member 1)
Diseases named in the same sentence as ABCB1 in open-access papers (continued):
Sharing a sentence is not in itself a finding about the gene and the disease.
epilepsy (94 papers, 2005 to 2026). A brain disorder characterized by episodes of abnormally increased neuronal discharge resulting in transient episodes of sensory or motor neurological dysfunction, or psychic dysfunction. "Future studies investigating the association between ABCB1 polymorphisms and antiseizure medication resistance should consider stratifying drug-resistant epilepsy patients by epilepsy type." (PMID 40565015, 2025). "We aimed to examine the relationship between SCN1A, GABRA1 and ABCB1 polymorphism and drug response in epilepsy children in Vietnam." (PMID 38674283, 2024). "The two single nucleotide polymorphisms of ABCB1 were found to be significantly associated with treatment outcomes of valproic acid in children with epilepsy." (PMID 38004402, 2023). "Polymorphisms in the ABCB1 gene encoding P-gp have been demonstrated to influence the outcome of epilepsy treatment." (PMID 38004402, 2023). "The relevance of ABCB1 polymorphisms to VPA-induced ADRs in children with epilepsy was further explored." (PMID 38004402, 2023). "The aim of this study was to investigate the association of ABCB1 polymorphisms with the efficacy of and adverse drug reactions to valproic acid among Chinese children with epilepsy." (PMID 38004402, 2023). "For instance, SE in dogs has been reported to increase Pgp in the canine brain and polymorphisms in the Pgp-encoding ABCB1 gene have been associated with seizure outcomes in Collies with epilepsy." (PMID 35812852, 2022). "Prior experimental work has linked ABCB1 activation and expression of its protein, P-gp, with cell hypoxia akin to what occurs “locally” in the surgical bed during brain surgery for epilepsy." (PMID 36188379, 2022). "Over the following years, many additional studies investigating ABCB1 polymorphisms in epilepsy were published, including recent meta‐analyses." (PMID 34486831, 2022). "The cited data from the literature indicate that there is no clear answer to the question regarding the role of the polymorphisms of MDR1/ABCB1 gene in drug-resistant epilepsy." (PMID 34769124, 2021). "While aging and AD showed chronic loss of certain transporters, in epilepsy a compensatory overexpression of ABCB1 and ABCG2 transporting xenobiotics and drugs out of the CNS is a common feature and appears associated with pharmacoresistance." (PMID 33916769, 2021). "The C3435T variant of the ABCB1 gene has been proposed as a crucial factor for drug resistance in epilepsy." (PMID 32357528, 2020). "In the present study, we noted a significant association of ABCB1 C3435T polymorphism with drug resistance in epilepsy." (PMID 31871496, 2019). "Several studies have demonstrated a link between ABCB1 gene variants and the response to treatment in epilepsy, but most studies have in fact been inconclusive." (PMID 28082152, 2018). "There have been associations reported for variation in other transporter-encoding genes and treatment-resistant epilepsy, but the strength of evidence is less still than that for ABCB1." (PMID 28082152, 2018). "Various studies have yielded contradictory findings regarding the relationship between ABCB1 C3435T polymorphism and AEDs resistance in epilepsy." (PMID 28202008, 2017). "Our meta-analysis concerned only the association between ABCB1 C3435T polymorphism and drug-resistant epilepsy, which revealed a significant risk to pharmacoresistance (OR = 1.877, 95% CI 1.213–2.905, P = 0.005)." (PMID 28202008, 2017). "Previous studies focusing on the association between ABCB1 C3435T polymorphism and drug-resistant epilepsy showed discordant findings." (PMID 28202008, 2017). "Characteristics of studies analyzed for meta-analysis of association between the C1236T, G2677T, and C3435T variants in ABCB1 gene and drug response in patients with epilepsy." (PMID 25816099, 2015).
epilepsy (continued). "Summary odds ratios and heterogeneity of the C3435T polymorphism in ABCB1 gene on drug response in patients with epilepsy stratified by age, language, ethnicity, sample size and date of publication." (PMID 25816099, 2015). "These evidences do indicate the potentiality of ABCB1 in increasing the risk of epilepsy but however, the exact mechanism still remains elusive and warrants further studies." (PMID 24586633, 2014). "An association between the ABCB1 gene and the development of epilepsy has been reported with an overrepresentation of C allele in patient group." (PMID 24586633, 2014). "These evidences indicate the the of ABCB1 variant with epilepsy susceptibility was ethnicity specific." (PMID 24586633, 2014). "Subsequent to this meta-analysis several studies have been added and a recently published study from South Indian epilepsy patients also reported ABCB1 C3435T association with T allele overrepresentation showing ethnicity specific association." (PMID 24586633, 2014). "A study done on the Chinese population of Beijing showed a high degree of linkage disequilibrium between G2677T and two other polymorphisms of the ABCB1 gene in relation to drug resistant epilepsy." (PMID 23717663, 2013). "The C3435T, a major allelic variant of the ABCB1 gene, is proposed to play a crucial role in drug resistance in epilepsy." (PMID 21747587, 2011). "In the ABCB1 c.2 677G>A polymorphism, allele “A” was associated with the drug-resistant phenotype in epilepsy patients (P = 0.03, OR = 0.31, 95% CI = 0.10–0.93)." (PMID 21747585, 2011). "We intend to critically review the inherent problems associated with epilepsy pharmacogenetic studies in general and with ABCB1 polymorphisms studies in particular." (PMID 21747582, 2011). "This study revealed that the polymorphisms and haplotypes of the ABCB1 gene might be associated with the treatment outcomes of valproic acid in Chinese children with epilepsy." (PMID 38004402, 2023). "It was initially reported that the CC genotype at ABCB1 3435, (impaired function) may be associated with drug resistant epilepsy." (PMID 33916769, 2021). "Therefore, we focus, in this work, on evaluating the relationship between the ABCB1 C1236T, G2677T, and C3435T polymorphisms and the pharmacoresistant epilepsy in Tunisian patients." (PMID 31871496, 2019). "A recent meta-analysis including 8,604 subjects from 30 studies identified a significant correlation between the ABCB1 C3435T polymorphism and drug-resistant epilepsy, a result that needs to be verified in a case-control study with a larger sample size, as acknowledged by the authors." (PMID 28082152, 2018). "Thus, an association between ABCB1 polymorphisms and P-gp expression and activity levels in patients with refractory epilepsy needs to be confirmed in brain tissue first before the role of ABCB1 polymorphisms in ASD resistance can be accepted." (PMID 28729850, 2017). "Thereby, the association between ABCB1 C3435T polymorphism and drug resistance epilepsy could be affected." (PMID 28202008, 2017). "However, future research is required to investigate those associations further and also to investigate the possible mechanisms of this ABCB1-polymorphism on drug resistant epilepsy in Border Collies." (PMID 26316206, 2015). "However, a significant association was observed between ABCB1 (C3435T) rs1045642 and risk of having epilepsy (MTLE-HS and JME pooled cohort; genotypic p-value = 0.0002; allelic p-value = 0.004)." (PMID 24586633, 2014). "Functionally significant association of drug target genes such as GABRG2 and SCN1A and efflux transporter gene ABCB1 to susceptibility to epilepsy in the present population needs to be seen in combination rather than isolation in evaluating therapeutic response." (PMID 24586633, 2014).
epilepsy (continued). "There are only pharmacogenetic studies in epilepsy in association with MDR1/ABCB1 polymorphisms, but their results could give some guidance about the impact of SNPs in MDR1/ABCB1 in the treatment of neuropathic pain." (PMID 23766564, 2013). "The ABCB1 gene encoding P-gp is located in C3435T of exon 26 of chromosome 7, and contains three polymorphic genotypes CC, CT, and TT, with the up-regulation of the CC gene leading to the overexpression of P-gp, ultimately causing resistance to AEDs in patients with epilepsy." (PMID 35290166, 2022). "Initial association of the ABCB1 C3435T variant in multi-drug resistant epilepsy patients lead to the notion that the drug resistance in epilepsy might be genetically determined, where homozygous genotype of the C allele was more likely to be multidrug-resistant than the T allele." (PMID 24586633, 2014). "Interestingly, we observed that ABCB1 variants have a role in predisposing to epilepsy." (PMID 24586633, 2014). "The patients with epilepsy were less likely to have the TT genotype compared with controls (concerning ABCB1 c.1236C>T) (ORTT vs. CC = 0.42; 95% CI = [0.19-0.91]; p = 0.019)." (PMID 42188675, 2026). "In conclusion, our study reveals a higher CBZ clearance in the presence of the ABCB1 1236T-2677T-3435T haplotype in pediatric epileptic patients, supporting the potential of personalized medicine in optimizing epilepsy treatment." (PMID 39846525, 2025). "Among these, only ABCB1 rs2032582 (G vs. A and GG vs. GA + AA) was found to be noteworthy in Caucasian epilepsy patients under FPRP or BFDP at the pre‐specified probability level of 0.001." (PMID 40746153, 2025). "In the present study, we aim to find the association of SNPs in three genes including SCN1A, GABRA1 and ABCB1 in Vietnamese children affected by epilepsy." (PMID 38674283, 2024). "In epilepsy, the overexpression of ABCB1 is proven to be an important factor for the limited efficacy of antiepileptic drugs, as these transporters reduce the effective drug concentration at the site of lesions." (PMID 38727275, 2024). "ABCB1 plays a role in oxcarbazepine resistance, as evidenced by the finding that brain levels of this transporter in treated epilepsy patients are inversely proportional to the levels of oxcarbazepine active metabolites." (PMID 38727275, 2024). "An earlier study in the European region reported that patients with drug-resistant epilepsy (DRE) were more likely to carry the CC genotype of ABCB1 C3435T compared with patients with drug-responsive epilepsy." (PMID 38004402, 2023). "Our research shows that, in epilepsy, seizure-induced glutamate release activates a prostaglandin-dependent signaling pathway leading to Abcb1 and Abcg2 upregulation at the blood-brain barrier." (PMID 36973040, 2023). "Targeting signaling steps in this pathway has the potential to prevent ABCB1 upregulation at the blood-brain barrier and thus overcome drug resistance in patients with epilepsy." (PMID 36973040, 2023). "One of the most common variants in the ABCB1 gene is the C3435T polymorphism in exon 26 of the MDR1(Multi-Drug Resistance 1) gene, which was correlated with drug resistance in epilepsy among Caucasians." (PMID 36768858, 2023). "ABCB1 significantly restricts brain uptake of some antiseizure drugs and limits their efficacy in the treatment of epilepsy." (PMID 36973040, 2023). "ABCB1 is a known multi-drug resistance gene that codes for P-glycoprotein (P-gp), an ATP-dependent efflux pump thought to contribute to drug-resistance in epilepsy by preventing ASMs from reaching their target sites across the blood brain barrier." (PMID 36188379, 2022). "Patients with drug-resistant epilepsy were more likely to have at ABCB1 3435 CC and CT genotypes than TT genotype." (PMID 33804537, 2021). "The ABCB1 G2677T T (rs1128503) and C3435T T (rs1045642) alleles and the TT, CTT, and TTT haplotypes are associated with drug-resistant epilepsy in specific populations." (PMID 32357528, 2020).
epilepsy (continued). "In summary, our study indicated that KCNQ1OT1 promotes drug resistance of AEDs in vitro through targeting the miR-138-5p/NF-κB/ABCB1 axis, providing a potential target for overcoming drug resistance in epilepsy." (PMID 31920517, 2019). "Using PET and magnetic resonance imaging, increased ABCB1 transport activity has been demonstrated in patients with drug-resistant epilepsy." (PMID 28961159, 2017). "Previous studies reported the associations between the ATP-binding cassette sub-family B member 1 (ABCB1, also known as MDR1) polymorphisms and their haplotypes with risk of response to antiepileptic drugs in epilepsy, however, the results were inconclusive." (PMID 25816099, 2015). "We assessed the role of ABCB1 and ABCG2 variants in AED resistance by comparing a uniform cohort of AED resistant MTLE-HS epilepsy patients with AED responsive JME epilepsy patients." (PMID 24586633, 2014). "The ATP-binding cassette (ABC) transporters, and especially ABCB1, are the focus of an international effort to establish their role in mediating drug resistance in a variety of human diseases including epilepsy." (PMID 24213830, 2014). "Further, the study also inquired the role of ABCB1 and ABCG2 in susceptibility to epilepsy by comparing the epilepsy cohorts with non-epilepsy controls." (PMID 24586633, 2014). "The P-gp encoded by the ABCB1 and ABCC2 genes are expressed in drug resistant patients with epilepsy." (PMID 23717663, 2013). "Similar to astrocytes, ABCB1 expression in microglia is low under physiological conditions, but has been shown to be increased in epilepsy (Löscher and Potschka, 2005)." (PMID 23494712, 2013). "In this study, using a strict phenotypic definition, we found an association between the intronic polymorphic variation (TA genotype in Ex17-76) in the ABCB1 gene with the CoA deposition in MTLE-HS in a cohort of south Indian epilepsy patients." (PMID 21747587, 2011). "All the studies done so far in ABCB1 polymorphisms and AED-resistance in epilepsy are candidate gene-based genetic association studies, either SNP based or haplotype based, with their inherent limitations." (PMID 21747582, 2011). "Five genes, ABCB1, ABCB4, CHRNA7, GABRA1, and GABRG2, are located within reported CNV regions and have been studied previously for their association with epilepsy as collected by HuGE." (PMID 21390307, 2011). "A similar distribution of ABCB1 SNPs observed in epileptic patients and healthy subjects support a lack of association between ABCB1 polymorphism and the risk of having epilepsy." (PMID 39846525, 2025). "This led to the transporter hypothesis of refractory epilepsy, which states that ABCB1 overexpression at the blood-brain barrier in epilepsy restricts antiseizure brain drug uptake, thus, leading to antiseizure drug resistance." (PMID 36973040, 2023). "Currently, the relationship between the ABCB1 genetic polymorphism and PHT plasma concentration as well as the epilepsy resistance remains unknown." (PMID 35290166, 2022). "The authors concluded that ABCB1 rs2032582 and rs1045642 polymorphisms may affect the therapeutic efficacy of LEV in epilepsy." (PMID 35455472, 2022). "Although still controversial, it seems most likely that specific polymorphisms in ABCB1 are not responsible for a significant influence in response to ASMs in epilepsy." (PMID 34486831, 2022). "ABCB1 protein affects the drug resistance and blood drug concentration of epilepsy patients." (PMID 35707480, 2022). "In addition, a number of in vivo studies suggest that ABCB1 expression is elevated in case of epilepsy and neurodegenerative disorders such as amyotrophic lateral sclerosis (ALS)." (PMID 33916769, 2021). "C1236T, G2677T, and C3435T polymorphisms in ABCB1 gene did not contribute to the VPA response in epilepsy; while a CT variant of C129T(rs3213619) polymorphism was related to lower plasma VPA concentrations but not to drug responsiveness." (PMID 33804537, 2021).
epilepsy (continued). "ABCB1 G2677T/A and C3435T may affect levetiracetam disposition and therapeutic efficacy in Uygur children with epilepsy." (PMID 34769124, 2021). "The authors suggested that if ABCB1 contributes to pharmacoresistance, modulating and possibly inhibiting ABCB1 activity could be explored as a therapeutic strategy for drug resistant epilepsy patients." (PMID 33916769, 2021). "This could be e.g. relevant for ABC transporter profiles, since it is known that the transporter ABCB1 can be upregulated during epilepsy." (PMID 32138745, 2020). "A meta-analysis performed earlier using allele frequencies from nine studies, ruled out an association between ABCB1 C3435T polymorphisms and the risk of developing epilepsy." (PMID 24586633, 2014). "We performed a meta-analysis by incorporating 18 studies including the present study representing global ethnicity we observe no statistical significance of the ABCB1 C3435T alleles in epilepsy." (PMID 24586633, 2014). "However, ABCB1 rs1045642 increases vulnerability to epilepsy with greater tendency for MTLE-HS in south Indian ancestry from Kerala." (PMID 24586633, 2014). "In epilepsy patients of Han Chinese, rs3789243, as Tag SNP, was also identified to be associated with drug resistance, but not with ABCB1 mRNA levels in the brain samples, despite a relatively weak association evidence in liver tissue." (PMID 23050008, 2012). "Our results demonstrate that ABCB1 polymorphisms are associated with CoA deposition in MTLE-HS patients in south Indian patients, and further substantiate the need to revise its role in epilepsy genetics." (PMID 21747587, 2011). "The findings of the third meta-analysis indicate that neither the C allele nor the T allele carriers of the ABCB1 C3435T polymorphism confer significant risk to drug resistance in epilepsy." (PMID 21747587, 2011). "Six of these studies, genotyping either ABCB1 3435 or the common haplotype combination, ABCB1 3435C>T-2677G>T-1236C>T, confirmed the association between the 3435 SNP or the three-SNP haplotype (containing the 3435 SNP) and AED-resistant epilepsy." (PMID 21747582, 2011). "As ABCB1 transports many anti-epilepsy drugs (AEDs) across the blood-brain barrier (BBB) that may alter the exposure and efficacy of AEDs in patients with refractory epilepsy, another recent study investigated potential use of ABCB1 regulatory miRNA to reverse ABCB1-mediated MDR to AEDs." (PMID 39114355, 2024). "Indeed, significant linkage disequilibrium was detected among C3435T, T1236C, and G2677T in ABCB1, proposing that the three loci jointly could affect drug responsiveness in epilepsy." (PMID 31366017, 2019). "Current evidences revealed that individual polymorphisms contained in the ABCB1 did not significantly influence the treatment outcome but rather the interaction between them could determine intractability in epilepsy." (PMID 31366017, 2019). "Such discrepancies in study results could imply that there is no true association between the ABCB1 C3435T polymorphism with ASD resistance in epilepsy." (PMID 28729850, 2017). "The peripheral overexpression of ABC transporter can be developed as an objective marker of drug resistant epilepsy and this could help in drug dose adjustments in patients as demonstrated by previous study where ABCB1 overexpression was used as guide for clinical treatment." (PMID 28961159, 2017). "ABCB1, but also ABCC1, ABCC2, and ABCC5, expression is increased in brains from medically intractable epilepsy patients, hinting at their role in the resistance to treatments." (PMID 38727275, 2024). "In drug-resistant epilepsy patients, the overexpression of ABCB1 and ABCC1 was found on reactive astrocytes and the overexpression of ABCB1-3 and ABCC4 was detected on endothelial cells." (PMID 38727275, 2024). "ABCB1 and ABCC1 have been detected in human tissue samples of focal cortical dysplasia and benign tumor lesions in therapy-refractory epilepsy patients." (PMID 38727275, 2024).